TF (transferrin)
Diseases named in the same sentence as TF in open-access papers (continued):
Sharing a sentence is not in itself a finding about the gene and the disease.
chronic kidney disease (34 papers, 2012 to 2026). Impairment of the renal function secondary to chronic kidney damage persisting for three or more months. "Several studies conducted in patients with various stages of chronic kidney disease (CKD) have investigated the association of iron status markers, such as transferrin saturation (TSAT) and serum ferritin, with kidney outcomes." (PMID 37880328, 2023). "This study investigated the relationships between hemoglobin, erythroferrone, hepcidin, erythropoietin, ferritin, transferrin saturation, and renal function markers across different stages of chronic kidney disease in comparison with healthy controls." (PMID 41227183, 2025). "In this post hoc subgroup analysis, we aimed to clarify the effect of ferric citrate hydrate on transferrin saturation in patients with chronic kidney disease and low transferrin saturation (< 20%) undergoing hemodialysis." (PMID 39229929, 2024). "We note that ferumoxytol elevates hemoglobin levels, transferrin saturation and ferritin levels in patients with chronic kidney disease, compared to conventional iron supplement formulations." (PMID 35156909, 2022). "Increased kidney proximal tubule (PT) cell cytosolic non-transferrin Tf-bound, i.e., labile iron has been shown to induce the generation of ROS in PT cells and this could contribute to the progression of proteinuric chronic kidney diseases." (PMID 36978919, 2023). "Recent studies have found that transferrin saturation (TSAT), a measure of available iron, is associated not only with anemia control but also with prognosis and the development of cardiovascular disorders in patients with chronic kidney disease (CKD)." (PMID 36615783, 2022). "We observed that ferumoxytol administration was beneficial relative to conventional iron supplement formulations in terms of hemoglobin level management, ferritin level, transferrin saturation and limiting treatment related TEAEs in patients with chronic kidney disease." (PMID 35156909, 2022). "Our investigation looks at hemoglobin levels, ferritin level, transferrin saturation, and treatment related Treatment Emergent Adverse Events (TEAEs) incidence in chronic kidney disease patients administered ferumoxytol compared to those in patients taking conventional iron supplement formulations." (PMID 35156909, 2022). "Indeed, antagonists including PRS-080, NOX-H94 and LY2928057 (a humanized monoclonal FPN antibody) can improve serum iron levels and transferrin saturation in clinical tests with healthy and chronic kidney disease patients." (PMID 34679725, 2021). "In conclusion, as fluid overload is a common denominator for serum hemoglobin and transferrin saturation, and is closely related to the reduction in kidney function, it is an important factor to consider in the management of renal anemia, at least in advanced chronic kidney disease." (PMID 30894885, 2018). "CKD = chronic kidney disease; CRP = C-reactive protein; Hb = hemoglobin; IQR = interquartile range; n = number of patients; SD = standard deviation; TSAT = transferrin saturation; WHO = World Health Organization." (PMID 30614439, 2019). "Cubilin and megalin are responsible for reabsorbing transferrin iron in the kidney urine collecting system and the influence of CUBN on chronic kidney disease in African Americans has been studied." (PMID 22761678, 2012). "IDA is generally defined by serum ferritin of <67.4 pmol/L and transferrin saturation (TSAT) <16%, while higher cutoffs of serum ferritin and TSAT are used to define IDA under inflammatory conditions such as chronic kidney disease (CKD)." (PMID 29596361, 2018). "CKD = chronic kidney disease; Hb = hemoglobin; IQR = interquartile range; n = number of patients; NS = not significant; SD = standard deviation; TSAT = transferrin saturation; WHO = World Health Organization." (PMID 30614439, 2019).
Hypertension (32 papers, 2010 to 2026). The presence of chronic increased pressure in the systemic arterial system. "Our results do not replicate those of a Chinese study including 8337 adults, where transferrin levels were positively associated with incident hypertension." (PMID 38715055, 2024). "Our data also showed an association between the presence of hypertension and lower than normal levels of albumin and transferrin." (PMID 37323150, 2023). "Several cross-sectional clinical studies have demonstrated that serum ferritin and transferrin are positively associated with the risk of hypertension." (PMID 36014764, 2022). "The risk of high blood pressure and incidence of hypertension were also found to be positively correlated with hemoglobin and transferrin levels according to a large longitudinal study in China." (PMID 36120592, 2022). "Furthermore, a cross-sectional study in China found that hemoglobin and transferrin levels were linked to the occurrence of hypertension." (PMID 36407469, 2022). "As intraocular pressure is a major factor associated with glaucoma, it was important to demonstrate that TF could also protect the retina from hypertension-induced neuropathy." (PMID 36361544, 2022). "The markers hemoglobin and transferrin, serum furin, unsaturated fatty acids, and neurohypotensin may have predictive significance for the onset of hypertension." (PMID 35655131, 2022). "The concentration of transferrin in CSF reflects brain iron availability and can serve as a biomarker in different diseases such as arterial hypertension, which has effects on the secretory capacity of the CP, resulting in lower transferrin levels in the CSF of the SHR with respect to WKY." (PMID 23401751, 2013). "Univariate linear regression showed that blood Mn level was correlated with age (β = −0.049, p < 0.001), smoking (β = −1.588, p = 0.009), hypertension (β = −1.470, p = 0.006), serum TIBC (β = 0.025, p < 0.001), serum transferrin (β = 0.029, p < 0.001), and eGFR (β = 0.036, p < 0.001)." (PMID 29077007, 2017). "In the present study, we observed an inverse correlation between serum TF-UP level and the presence of AIS, and found that a decrease in the serum TF-UP/LRP ratio was related to an increase in the positive rate of AIS, adjusting for age, DM, hypertension and previous IHD." (PMID 33633672, 2021).
Cirrhosis (31 papers, 2005 to 2025). A chronic disorder of the liver in which liver tissue becomes scarred and is partially replaced by regenerative nodules and fibrotic tissue resulting in loss of liver function. "Prealbumin and transferrin levels have also been reported to be useful in stratifying mortality risk in patients with cirrhosis." (PMID 39927287, 2025). "According to the literature, in individuals with C282Y homozygosity, a transferrin level greater than 45% identifies 97.9%-100% of cases, and a ferritin level exceeding 1,000 ng/mL (1,390 ng/mL in our patient) is associated with an increased risk of cirrhosis and other complications." (PMID 40583922, 2025). "However, as ALD progresses and liver scarring occurs, low transferrin levels could be due to increased inflammation (inflammation reduces transferrin levels) and/or cirrhosis and reduction in the functional liver mass caused by alcohol-induced liver damage." (PMID 36214835, 2022). "A possible explanation could be that low serum TF is associated with cirrhosis." (PMID 32557671, 2020). "Another case report describes a 64-year-old man diagnosed with hereditary spherocytosis presenting with cirrhosis with markedly high serum ferritin and transferrin saturation." (PMID 39867034, 2024). "In the subcohort where iron, ferritin, and transferrin levels were known, the 23 patients with cirrhosis tended to have higher ferritin (p = 0.084), significantly higher iron (p = 0.014) and lower transferrin levels (p = 0.002)." (PMID 39200147, 2024). "As expected, patients with cirrhosis had significantly lower serum concentrations of albumin, transferrin, transthyretin, pseudocholinesterase, and apolipoprotein AI compared to healthy individuals." (PMID 36652164, 2023). "Immunohistochemical and biochemical tests confirmed reduced HNF4α and transferrin protein levels in individuals with cirrhosis." (PMID 33593348, 2021). "Observation of transferrin level changes in our study, highlight the importance of iron metabolism in cirrhosis since transferrin produced by hepatocytes is a crucial member of iron metabolism." (PMID 28439208, 2016). "Among all 88 patients with cirrhosis, 13 (14.8%) had low transferrin saturation, and 8 patients (9.1%) had IDA." (PMID 26261697, 2015). "Transferrin is mainly produced by the liver when hepatic regeneration takes place, as occurs in cirrhosis." (PMID 15745444, 2005). "In addition, serum transferrin was negatively related to liver fibrosis/cirrhosis (odds ratio 0.50, per SD unit increase; 95% CI 0.25–0.97, P = 0.041) and malignant neoplasm (odds ratio 0.42, per SD unit increase; 95% CI 0.21–0.86, P = 0.018)." (PMID 36185655, 2022). "Cirrhosis may lead to poor chromatographic and electrophoretic separation of transferrin isoforms leading to di‐ and tri‐sialotransferrin bridging, which impairs the interpretation of CDT as a marker of (heavy) alcohol consumption in these patients." (PMID 33190239, 2021). "Indeed, transferrin is lower in patients with cirrhosis, fatty liver disease and impaired synthetic function; low transferrin and high ferritin, a combination that, in the present study, is seen for tramadol, may indicate inflammation." (PMID 32664348, 2020). "The lag time and endogenous thrombin potential (ETP) were comparable between healthy subjects and cirrhosis patients, whereas the peak height and velocity index were significantly elevated in patients, irrespective of the TF concentration used." (PMID 28472132, 2017). "In addition, transferrin, BCHE, and apolipoprotein AI but not albumin and transthyretin display a stage-dependent decrease of serum concentrations from stable (SDC) and unstable decompensated cirrhosis (UDC) to pre-ACLF and ACLF as indicated by a significant Jonckheere-Terpstra test." (PMID 36652164, 2023).
prostate carcinoma (30 papers, 2014 to 2026). A carcinoma that arises from epithelial cells of the prostate gland. "A total of 260,189 participants (including 2,906 cases) were included in our meta-analysis, which revealed statistically significant associations of increased serum ferritin and transferrin saturation levels with the decreased risk of prostate cancer." (PMID 36561528, 2022). "Accumulating observational studies have explored the associations of serum iron biomarkers (iron, ferritin, transferrin saturation, and transferrin) with the risk of prostate cancer." (PMID 36561528, 2022). "A total of 10 articles (six retrospective studies and four prospective studies) were identified, which investigated the association of serum iron, ferritin, and transferrin saturation with the risk of prostate cancer." (PMID 36561528, 2022). "Taken together, these results strongly suggest that TF antigen expression in prostate cancer cells is associated with the stem cell like phenotype." (PMID 29228713, 2017). "One remarkable outcome of this analysis was that a significant fraction of glycoproteins identified as cell surface TF-antigen carriers in PC-3 and DU-145 cells are associated with stem cell phenotype or function, including prostate cancer stem-like cells." (PMID 29228713, 2017). "The large sample size gave us adequate power to estimate the potential causal relationship between iron status and risk of prostate cancer, with 0.87 for serum iron, 0.88 for log-transformed ferritin, 0.89 for transferrin saturation, and 0.86 for transferrin, respectively." (PMID 36561528, 2022). "Search by genomic interval applied to the genomic interval that includes the SNPs and the IRX4 promoter, identifies TF ChIP-seq peaks in prostate cancer cell lines, which are then be displayed on the data browser." (PMID 37971305, 2024). "PSA colocalises with motor protein myosin VI in transferrin-positive recycling endosomes in prostate cancer cells, and its secretion was reduced when myosin VI was knocked down, highlighting a critical role for endosome transport in modulating PSA secretion." (PMID 39796673, 2024). "Various bioinformatic integrative analyses identified candidate target genes, miRNA, and TF as signatures in prostate cancer." (PMID 36982429, 2023). "These novel transferrin-bearing, zein-based hybrid lipid nanoparticles therefore exhibit promising potential as drug and gene delivery systems for prostate cancer therapy." (PMID 38004621, 2023). "Tumor TF expression (H‐score) was generally comparable between the first and second biopsy in patients with cervical, ovarian, and prostate cancer, although differences in H‐score were observed between T1 and T2 for individual patients." (PMID 36806722, 2023). "A label-free protein expression approach was used to assess the glutathione-thioredoxin antioxidative pathway in a prostate cancer cell line (PC-3) after exposure to gold nanoparticles conjugated with a targeting moiety (transferrin)." (PMID 37627612, 2023). "Several studies highlighted a role for tumor-derived EVs expressing TF and PS in the thrombotic manifestations of many cancers including multiple myeloma, and breast and prostate cancers." (PMID 36013171, 2022). "For example, a case-control study in America including 34 prostate cancer cases and 84 controls suggested that serum iron, ferritin, and transferrin saturation levels were lower in patients with prostate cancer than that in controls." (PMID 36561528, 2022). "On the contrary, a case-control study in America including 34 patients with prostate cancer and 84 controls reported lower serum iron, ferritin, and transferrin saturation in patients with prostate cancer than that in controls." (PMID 36561528, 2022). "Noteworthy, among the plethora of cellular effects, transferrin itself, has also been suggested to regulate e-cadherin and beta-catenin in prostate cancer cells." (PMID 34884287, 2021).
prostate carcinoma (continued). "CK2 inhibition (DMAT, TF, TBB, TBCA, siRNA, apigenin, and KI-CK2α) reduces cell proliferation in prostate cancer cell lines, and TF, CX-4945, DMAT, TBB, TBCA, and apigenin increase apoptosis." (PMID 28134850, 2017). "The results presented in this study suggest that multiple subpopulation of putative prostate cancer stem-like cells characterized by distinct molecular signatures can be attacked using a single target commonly expressed on these cells, the TF-Ag." (PMID 29228713, 2017). "This outcome strongly suggests that there is a link between TF-Ag expression and prostate cancer stem-like phenotype." (PMID 29228713, 2017). "The integrated TF-miRNA regulatory networks reveal some interesting information about molecular interactions in the primary and metastatic state of prostate cancer." (PMID 28005952, 2016). "One such network was derived for each of the clinical states of prostate cancer based on differentially expressed and significantly correlated gene, miRNA and TF pairs from the patient data." (PMID 28005952, 2016). "In a prostate cancer preclinical model, transferrin-conjugated PLGA NPs with encapsulated paclitaxel displayed better anti-tumor activity than either free paclitaxel or NPs with paclitaxel that did not have the transferrin conjugation." (PMID 28347089, 2015). "These novel transferrin-bearing zein-based hybrid lipid nanoparticles therefore hold promising prospects as a novel approach for prostate cancer treatment and warrant further investigation to assess the combination of docetaxel and plasmid DNA for cancer therapy." (PMID 38004621, 2023). "Coculturing prostate cancer cells with high TF expression with peripheral blood mononuclear cells and platelets enhanced EVs TF activity while no such observation was shown in prostate cancer cells with low TF expression." (PMID 36013171, 2022). "Indeed, a simple analysis of the cell surface signatures discovered in recent years for putative prostate cancer stem cells by different groups reveals that every one of these signatures contains at least one, or two, or even three TF-Ag glycoprotein carriers." (PMID 29228713, 2017). "Similarly, TF+ DU-145 cells exhibited stronger propensity to clonogenic survival and growth than their TF- counterparts indicating that TF-Ag selection does enrich for prostate cancer cells with enhanced clonogenicity." (PMID 29228713, 2017). "It appears that TF antigen could be a common denominator for multiple populations of prostate cancer stem like cells identified to date and otherwise characterized by distinct cell surface signatures." (PMID 29228713, 2017). "Also, liposomes functionalized with transferrin (TF) developed for the delivery of Dtx may show advantages in the treatment of prostate cancer." (PMID 35625921, 2022). "Furthermore, a γ-TF-rich mixture of TFs was found to suppress the incidence of palpable tumors and maintained redox sensitive transcription factor Nrf2, as well as Nrf2-regulated antioxidant genes in a murine prostate cancer TRAMP model." (PMID 33919211, 2021). "Thus, in this study we have performed the analysis of cell surface prostate cancer TF proteome." (PMID 29228713, 2017). "Consequently, TF antigen specific therapeutics such as anti-TF antibodies or TF-Ag binding peptides could potentially provide means for targeting simultaneously multiple prostate cancer stem cell subtypes." (PMID 29228713, 2017). "Consistently, we found lower serum ferritin (SMD: −1.25; 95% CI: −2.34, −0.16; P = 0.024) and transferrin saturation (SMD: −1.19; 95% CI: –2.34, −0.05; P = 0.042) levels in patients with prostate cancer compared with that in controls." (PMID 36561528, 2022). "Results from our meta-analysis similarly showed that serum ferritin [standardized mean difference (SMD): −1.25; 95% CI: −2.34, −0.16; P = 0.024] and transferrin saturation (SMD: −1.19; 95% CI: −2.34, −0.05; P = 0.042) were lower in patients with prostate cancer compared with that in controls." (PMID 36561528, 2022).
prostate carcinoma (continued). "Increasing the LIP by supplying Fe2+, as holo-TF or FAS, sensitized prostate cancer cells to VC." (PMID 36139668, 2022). "To interrogate this question, we have used magnetic activated cell sorting (MACS) with biotinylated anti-TF-Ag antibody JAA-F11 to isolate TF-Ag-positive (TF+) and TF-Ag-negative (TF-) prostate cancer cells." (PMID 29228713, 2017). "In a recent study, 2-D DIGE gel electrophoresis coupled with MS and bioinformatics analysis identified serotransferrin (TF), alpha-1-microglobulin/bikunin precursor (AMPB) and haptoglobin (α-chain) (HP) as new urinary biomarkers, which could distinguish between BPH and prostate cancer." (PMID 30197761, 2018). "In prostate cancer, however, the TF proteome has not been investigated systematically until now." (PMID 29228713, 2017). "With regard to metastatic castration-resistant prostate cancer, though there are no ADCs approved for prostate cancer, there are some ADCs targeting different antigens in clinical studies, such as PSMA, TROP-2, STEAP1, TF and DLL-3." (PMID 40959458, 2025).